CD4 (CD4 molecule)
Diseases named in the same sentence as CD4 in open-access papers (continued):
Sharing a sentence is not in itself a finding about the gene and the disease.
infection (continued). "Indeed, a recent study has shown distinct differences in CD4+ and CD8+ cytotoxic responses to TB10.4 in a mouse model of TB infection: similar levels were seen early in infection with the CD4+ response decreasing at later stages and the CD8+ response increasing." (PMID 20574540, 2010). "The lymphoid tissue contains more than CD4 T cells, i.e., the ratio of virus to CD4 cells in the LT is approximately 1∶1, and virus particles will bind CD4 T cells and macrophages, and defective virus particles will be “cleared” by non-productive infection." (PMID 20824126, 2010). "Additionally, mice lacking CD4+ T cells had reduced IgG production and, later in infection, WNV-specific CD8+ T cell activation and trafficking to the CNS were compromised." (PMID 20661470, 2010). "Thus, as CD4+ cells, CD8+ cells can be redistributed across the cell cycle upon infection." (PMID 20222966, 2010). "CD3+CD4+ T cells increased after infection in WTbut not in PAFR KO mice (Fig4G)." (PMID 21079759, 2010). "Interestingly, superantigen-induced synapses between Jurkat cells and Raji/CD4 cells did not enhance infection for either HTLV-1 or HIV-1." (PMID 20195464, 2010). "Previously, we proposed that early infection with FIV may be dominated by viruses with a complex, high affinity interaction with CD134 and which target cells where CD134 is abundant (activated CD4+ T cells) and which have a restricted cell tropism." (PMID 20420700, 2010). "Although in several infectious disease models including T. gondii, primary CD8+ T cell response during acute infection phase has been shown to be independent of CD4+ T cell help, the role of CD4+ T cells themselves in partially mediating protection against T. gondii cannot be discounted." (PMID 20520779, 2010). "The enhanced and early production of CXCL10 that we observe in Mtb-infected IL-10−/− mice may contribute to the increased number of IFN-γ-producing CD4+ T cells recruited to the lungs, in keeping with the known role of CXCL10 in Th1 migration during other infections." (PMID 20518032, 2010). "Thus, a longer infection time was unlikely to account for the presence of high avidity CD4+ T cells in the controller group." (PMID 20195518, 2010). "A number of observations suggest that CD4 T cell depletion in HIV is not only related to direct, virus-mediated death of infected cells but also to cell death of a large number of uninfected bystander T cells in the setting of increased activation that follows infection with HIV." (PMID 20689824, 2010). "Furthermore, a new study shows that the chance of misclassification is much higher for individuals indicated to start therapy and with low CD4 cell counts, than those with established infection but without symptoms." (PMID 19479050, 2009). "However, CD4+ T cell responses against this epitope waned as the infection progressed and were no longer detected at later time points." (PMID 19165342, 2009). "However, in latently infected resting CD4 T cells, when cells were activated at day 5 post infection, only the wild-type virus but not the VSV-G-pseudotyped HIV-1 was induced to replicate." (PMID 19851458, 2009). "Finally, i.p. infection of CXCR2−/− mice with JHMV did not affect the generation of virus-specific CD4+ or CD8+ T cells compared to infected CXCR2+/+ mice." (PMID 19893623, 2009). "Indeed in HIV-1 infected individuals, there is an increase in the proinflammatory lymphocyte response as well as an absence of CCR5+ CD4+ T cells within the GI tract during the acute stage of infection." (PMID 19674458, 2009). "However, early mucosal depletion of memory CD4+ T cells is also observed in nonpathogenic infection of natural African monkeys such as African green monkeys and sooty mangabeys." (PMID 19360097, 2009).
infection (continued). "The steady rise of the percentage of GFP-expressing rat CD4 T-cells over the course of the HIV-1R7/3 YU-2 Env GFP infection was sensitive to the addition of the reverse transcriptase inhibitor efavirenz (EFV) 18 h post-challenge, which inhibited viral replication subsequent to first-round infection." (PMID 19144136, 2009). "In the lungs, CD4/10.4 cells expanded rapidly and reached around 3% of all T cells (5.5% of all CD4 T cells, data not shown) 4–6 weeks after infection, which represented a significant increase in CD4/10.4 cell numbers compared to week 0 post infection (student's T test, p<0.05)." (PMID 19529765, 2009). "This may also explain why X4 has trouble initiating infection when R5 virus is absent: CXCR4's per-cell density on the most crucial memory CD4+ T cell population is simply too low." (PMID 19680436, 2009). "The overwhelming CD4+ T cell responses seen in our in vitro priming are consistent with the strong and broad CD4+ T cell responses we have observed in individuals with acute HIV-infection and which disappeared or were greatly reduced within three months after onset of infection." (PMID 19165342, 2009). "However, it has also been reported that the majority of CD4+ T cells dying during the infection are not productively infected with HIV-1." (PMID 18617991, 2008). "Although FIV-specific lymphoproliferative responses were markedly increased, viral loads and CD4+ T cell depletion were unaffected, thus indicating that boosting antiviral cell-mediated immunity may not suffice to modify infection course appreciably." (PMID 18416857, 2008). "Here we have examined the role of natural and adaptive regulatory T cells in the control of malaria infection and find that classical CD4+CD25hi (and Foxp3+) regulatory T cells do not significantly influence the outcome of infections with the lethal (17XL) strain of Plasmodium yoelii (PyL)." (PMID 18401464, 2008). "Hematologic tests of our patients showed a reduction of CD4+ cells in III-4, a reduction of CD8+ cells in IV-4, and a slight reduction of serum IgG levels in adult patients, but none of our patients showed susceptibility to infection." (PMID 18489790, 2008). "If one assumes that all FoxP3+ cells, regardless of CD25 expression, have the same frequency of infection as CD25hiFoxP3+ CD4+ T cells, one can estimate the relative size of the Treg reservoir as potentially ranging from 3.1 to 38.6% of the total resting CD4+ T cell reservoir." (PMID 18827929, 2008). "Productive infection of T-lymphoblastoid cells by X4 HIV-1 markedly reduces cell-surface expression of CD4, but whether or not the co-receptor CXCR4 is down-regulated has not been conclusively determined." (PMID 18190699, 2008). "Our present results with HIV-1 Ba-L and HIV-1 A204 are consistent with that model for BeWo-CD4 positive cells, as a dose-dependent inhibition of viral entry was observed, though with IC50s that are 1,000 fold higher than those reported for classical HIV-1/PBMC infection." (PMID 18377645, 2008). "Because dendritic cells constantly interact and stimulate CD4 T cells, even infrequent transmission of intact HIV particles during cellular communication events can result in efficient dissemination of HIV from the very cells that are designed to control its infections." (PMID 18725936, 2008). "Indeed, a recent report suggests that Langerin-positive dendritic cells degrade internalized HIV-1, reducing transfer to CD4+ T cells in the mucosa, while others show that activated CD34-positive Langerhans cells increase trans infection of permissive target cells." (PMID 18637194, 2008). "Comparable neutralizing antibody activity was observed in WT and IL-6−/− serum analyzed 8 weeks post infection thus the impairment in the CD4+ T cell memory response observed in the IL-6−/− mice did not impinge on their ability to generate adequate neutralizing antibodies." (PMID 18389078, 2008).
infection (continued). "Furthermore, adoptive transfer of CD25+ and/or CD25− CD4+ T cells into RAG−/− mice also failed to reveal any role for CD25+ Foxp3+ cells in this infection." (PMID 18401464, 2008). "Thus, DCs facilitate productive infection of CD4 T cells while not serving as hosts for viral replication." (PMID 18584030, 2008). "This showed that although on day 7 p.i. there were more lymphocytes recruited to lungs infected with v-176WT compared with infection with vH1 or v176-NHA, CD3+ T cells were less activated, and this was reflected by a lower level of the activation marker CD69+ on both CD4+ and CD8+ lymphocytes." (PMID 17485525, 2007). "Analysing other infection models might give some more insights about the role of CD4 T helper cell tolerisation on antibody responses during infection with persistence prone viruses, however this still is not representative for HIV or HCV infection in humans." (PMID 18000535, 2007). "Interestingly, increases in numbers of CD4+ T cells did not follow the same pattern and were somewhat reduced in infections initiated by mosquito transmission, perhaps reflecting the reduced PAMP or antigenic stimulus of lower parasitaemia." (PMID 17555592, 2007). "It is tempting to speculate that the low or non-productive infection of non-CD4-expressing cells may be amplified by contact with T-lymphocytes in vivo." (PMID 17645788, 2007). "We hypothesized that SHIVSF162P4–induced CC-chemokine down-regulation at acute stage of infection was not proportionately related to peripheral CD4+ T cell depletion as a result of viral target cell destruction." (PMID 17684570, 2007). "Considering neutralization sensitivity of these isolates, newly infected macaques often harbored virus populations with a CD4-independent-HIGH and neutralization sensitive phenotype that changed to a CD4-independent-LOW and neutralization resistant virus population in the course of infection." (PMID 17645788, 2007). "However, productive infection in NP-2 cells expressing CCR5 but not CD4 was in most cases revealed only after cocultivation of infected NP-2/CCR5 cells with hPBMC (CD4-independent-LOW)." (PMID 17645788, 2007). "Furthermore, productive infection was readily observed in CD4+ T cells but not in LC emigrating from the vaginal epithelium." (PMID 17306567, 2007). "Additionally, mice lacking CD4+ T cells had reduced IgG production and, later in infection, compromised WNV-specific CD8+ T cell activation and trafficking to the CNS." (PMID 18000543, 2007). "Considering the background of immune activation reported in African populations, we asked whether differences in the levels of CD4 T cell activation and in the capacity to replicate HIV-1 in vitro could be related to the apparent resistance to infection in this group." (PMID 16792805, 2006). "In this study we have demonstrated that when the HIV-1 was incubated with the crude saliva and purified salivary MUC5B and MUC7 mucins and subsequently added to the CD4+ CEM SS cells no viral replication or infection of the CEM SS cells was detected by the p24 antigen assay." (PMID 17125499, 2006). "In summary, although CD4+ T cells in the peripheral blood have been reported to fully reconstitute in patients on ART, there is considerable controversy regarding the capacity for restoration of intestinal CD4+ T cells, particularly for patients treated in the early stages of infection." (PMID 17147469, 2006). "It is not necessarily clear how an infection initiated in this manner might spread to other CD4+ T cells but migrating dendritic cells or macrophages could carry the infection back towards the large T cell populations in extrafollicular areas." (PMID 16600047, 2006). "Therefore, CD4(-) cell infection can be gp120-independent; i.e., the presence of gp120 glycoprotein molecules on the viral surface is not crucial for CD4(-) cell infection." (PMID 16368003, 2005).
infection (continued). "Moreover, in vitro stimulation with concanavalin A or αCD3/CD28 antibodies failed to increase CCR5 expression in CD4+ T cells from SMs, especially in the Tcm (central memory) compartment, which showed therefore protection from infection even in the presence of activation signals." (PMID 39842407, 2025). "Notably, when transwell inserts prevented direct contact of the HIV-1-infected macrophages with the non-infected CD4+ T cells, we did not observe any enhancement of macrophage infection nor did we see CD4+ T cell infection or increased p24 production in cell culture supernatants." (PMID 40130873, 2025). "This suggests that CD4+ T cell proliferation is the major source of reservoir cell generation during ART and likely contributes during early and chronic untreated HIV, though the proportion of reservoir cells generated by proliferation versus infection pre-ART is unknown." (PMID 40464563, 2025). "The lack of significant evolution in the env gene during the infection phase could also explain the lack of increased viral replication capacity and depletion of CD4+ T cell that were observed, which was expected as we had observed in a previous infection study." (PMID 40007032, 2025). "Furthermore, total ICs exhibited significantly lower levels on activated (HLA-DR+/CD38+) CD4+ T cells during the chronic phase (133 days post-infection) and on activated CD8+ T cells during the acute and chronic infection phases (49, 84, and 133 days post-infection) in ECs." (PMID 40637373, 2025). "While local IFN-γ production might be necessary for full control of infection in B6 mice, additional research has shown effects of T cell-mediated IFN-γ independent mechanisms that contribute to control of infection, including through GM-CSF production by CD4 T cells and the production of IL-17." (PMID 40937719, 2025). "Importantly, most results have shown that macaque species may also lose their CD4+ T cells after infection with SIVagm23,24 or SIVsmm, while natural SIV hosts avoid pathogenesis after infection with SIVmac26 or recombinant SIVagm including HIV-1-specific virulence factors." (PMID 39842407, 2025). "In addition, depletion of CD96 from CD4+ T cells did not alter basic parameters of virus replication, i.e., infection rate, virus production, and HIV-1 infectious particle release, even when Nef and Vpu were inactivated rendering the virus inactive in CD96 down-regulation." (PMID 40911682, 2025). "Since only about 20% of cervical lesions have been reported to be caused by HPV 18 from previous studies, the authors hypothesised that HPV 18 infects a higher percentage and that some of the E6 responsive HPV 18 negative patients may have cleared the infection and developed CD4+ T cell memory." (PMID 40589751, 2025). "Furthermore, when stratified according to infection history (no prior infection, infection with pre-Omicron variants, Omicron variants, or both), CD4+ and CD8+ T cell responses remained consistent, regardless of infection history for both WT and BA.4/BA.5 in vitro stimulations." (PMID 40869428, 2025). "With the outcome event as the dependent variable, Gender, Age, Ethnicity, Edu-cation, Marital status, Occupation, Route of infection, Sample Source, CD4+T lymphocyte count and Whether or not treated with ART as independent variables, a univariate analysis was conducted." (PMID 41567789, 2025). "Moreover, we detected an increase in Active memory B cells and CD8+ cells in the early phases of infection, and a reduction in CD4+ T-cells in the mpox patients with respect to the controls and found the presence of higher levels of Treg cells in the HIV+ patients in the early phase of infection." (PMID 40005722, 2025).
infection (continued). "Previous research revealed higher CD4+ helper T/Th memory, CD8+ cytotoxic T/Tc memory, and B memory cells in the recovered individuals at 45–60 days postrecovery compared to mild symptomatic patients and suggested that it could be proposed as markers/indicators of recovery from mild infection." (PMID 39963186, 2025). "The usage of CP caused significant reductions in the numbers of B and CD4+ T cells and a slight, not significant, reduction tendency in the case of AMs and CD8+ T cells in the lung of control and EGR2-deficient mice compared with the nonimmunocompromised infection." (PMID 39042472, 2024). "Interestingly, only mice born to L.rh supplemented mothers further displayed an increased activation of IFN-γ producing virtual memory CD8 T cells and a production of IL-10 by CD4 and CD8 T cells that could explain a better control of the lung damages upon infection." (PMID 39710590, 2024). "We first investigated this hypothesis using an in vitro model of HIV latency whereby resting CD4+ T cells were infected in the presence of dendritic cells, a model which favors latent over productive infection and is able to distinguish between proliferating and nonproliferating‐infected cells." (PMID 39248154, 2024). "However, M09-specific cells are the only known herpesvirus-specific CD4 T cells not efficiently primed during the first weeks of infection, although examples of this do exist in polyoma virus and LCMV infection, and therefore we have defined them as ‘late-rising’." (PMID 38236791, 2024). "Conversely, in the A2.DR1 mouse model, MVA-spCTH522 vaccination may help elucidate the role of CD4+ and CD8+ T-cell responses, while MVA-CTH522:B7 may determine whether the combined involvement of CD4+ T cells, CD8+ T cells, and antibody responses is critical for protection against infection." (PMID 39204067, 2024). "Overall, this study suggested an Sh-associated decrease in MTB specific Th1 CD4+ T cell function, with associated increases in Th2 cells, raising concern for a compromised immune response to MTB in individuals with Sh infection which may not be entirely reversed after treatment." (PMID 39250522, 2024). "Merely looking in the peripheral blood of HCMV+ individuals at virus epitope specific CD4 T cells would not answer this question, as in most cases infection occurred several years ago, but including a kinetic analysis in vaccinated or transplanted HCMV- cohorts could start to assess this." (PMID 38236791, 2024). "Interestingly, control mice showed comparable numbers of splenic NKG2D+CD4+ T cells before Lpn infection but these were not recruited to the lung and could not mediate heterologous protection upon challenge." (PMID 38838013, 2024). "Transport of the HIV-1 genome across an intact nuclear membrane is a key factor in productive infection of non-dividing cells, such as resting CD4+ T cells and macrophages, removing the requirement for nuclear dissolution during cell division that other retroviruses may require." (PMID 39205255, 2024). "Thus, diverse and polyfunctional SARS2-specific CD4+ and CD8+ T cell responses, including CD4+ and CD8+ T cells with profiles of cytotoxicity, may play a role in viral clearance during acute SARS-CoV-2 primary infection." (PMID 39704169, 2024). "Interestingly, the survey of the kinetics of CD4+ T helper cell responses in blood demonstrated a Th1 (Tbet+CD27-) dominated immune response, and only a weak increase of Th2 (CD27-GATA3+) cells in the circulation at 2-4 weeks post-infection that resolved during chronicity." (PMID 38799456, 2024). "Therefore, a lack of CD4+ T cell help or CD40L signaling during early infection might also impact the B cell response." (PMID 39392861, 2024).